IL33 (interleukin 33)
Diseases named in the same sentence as IL33 in open-access papers (continued):
Sharing a sentence is not in itself a finding about the gene and the disease.
pulmonary fibrosis (continued). "IL-33 promotes ST2-dependent lung fibrosis by inducing macrophage activation and enhancing ILC2s expansion." (PMID 27547445, 2016). "Studies of Cryptococcus neoformans infection 25, bleomycin‐induced lung fibrosis 26 and ovalbumin‐induced airway inflammation 13, 27 have demonstrated a role for IL‐33 in the alternative activation of lung derived or alveolar macrophages." (PMID 27592711, 2016). "Exogenous IL-33 increased severity in bleomycin-induced lung fibrosis, whereas inhibition of IL-33 pathways reduced lung fibrosis, as assessed by anti-IL-33 treatment in the bleomycin model or in ST2 KO mouse responses to bleomycin." (PMID 27703303, 2016). "Patients with idiopathic pulmonary fibrosis have also been reported to have elevated levels of IL-33 in BAL and lung tissue compared to healthy controls." (PMID 27001429, 2016). "Large numbers of cells expressing abundant IL-33 are observed in the lungs of patients with idiopathic pulmonary fibrosis, as well as systemic sclerosis." (PMID 26549942, 2015). "Similarly, one study showed that IL-33 promotes pulmonary fibrosis by directly acting on two of the most important cell types during fibrosis: alveolar epithelial cells and (myo)fibroblasts." (PMID 39925809, 2025). "In BLM-induced pulmonary fibrosis, IL-33 is expressed in the lung and promotes injury and fibrosis." (PMID 39286257, 2024). "To understand the role of IL-33 in established pulmonary fibrosis, we assessed the localisation of IL-33 in fibrotic lung tissue and determined whether IL-33 expression by HLFs could be regulated by TGFβ." (PMID 36949463, 2023). "In the same study, the authors evaluated the concentrations of IL-33 in epithelial lung tissue from the explanted end-stage lungs of CF subjects and non-CF patients affected by lung fibrosis and primary pulmonary hypertension and lung fibrosis." (PMID 36675299, 2023). "The cytokine IL-33 wears conflicting conclusions on the pulmonary fibrosis driven by bleomycin." (PMID 36403186, 2023). "In contrast to our findings in LoS patients, serum IL-33 levels were reported to be elevated in patients with SSc compared with healthy controls and correlated with the extent of skin sclerosis as well as with the severity of pulmonary fibrosis." (PMID 36362603, 2022). "IL‐33/ST2 promotes lung fibrosis by potentiating M2 macrophages skew." (PMID 36082495, 2022). "IL-33 can also induce pulmonary fibrosis by promoting ST2/IL-13/IL-4Rα-mediated AAM activation." (PMID 36362440, 2022). "IL-33 levels correlated with the extent of skin sclerosis and the severity of pulmonary fibrosis." (PMID 35042522, 2022). "For example, the cytokines IL-25 and IL-33 produced by epithelial cells induce Th2-type adaptive responses where increased expression of both cytokines has been found in patients with idiopathic pulmonary fibrosis (IPF), and IL-33 has an inhibitory effect on mast cell functions." (PMID 33562816, 2021). "Inversely, exogenous IL-33 or adoptive transfer of ILC2s enhanced BLM-mediated pulmonary fibrosis." (PMID 32390869, 2020). "IL-33 from epithelial cells is involved in pulmonary fibrosis." (PMID 32793232, 2020). "A profibrogenetic role of IL-33 has been demonstrated for pulmonary fibrosis (idiopathic and SSc-related fibrosis), liver fibrosis (cirrhosis, viral hepatitis, primary biliary cirrhosis, and NASH), pancreatic fibrosis, intestine fibrosis (IBD), renal fibrosis, and skin fibrosis." (PMID 32679721, 2020). "Moreover, they reported that SSc patients with pulmonary fibrosis and decreased forced vital capacity presented higher IL-33 levels." (PMID 31766607, 2019). "Regarding pulmonary fibrosis mature IL-33 enhances pro-fibrogenic type 2 cytokine production in an ST2- and macrophage-dependent manner, while full-length IL-33 is also implicated in the pulmonary fibrotic process in an ST2-independent, Th2-independent fashion." (PMID 30405626, 2018).
pulmonary fibrosis (continued). "Given the clear importance of IL-1α, IL-1β and IL-33 in lung fibrosis and the likely compensatory action provided by members of the IL-1 cytokine family in vivo, targeting the shared receptors (for example, IL-1RAcP) may be more effective." (PMID 27001429, 2016). "In addition, serum IL-33 levels are elevated in patients with systemic sclerosis and correlated with the extent of skin sclerosis and the severity of pulmonary fibrosis." (PMID 27001429, 2016). "In the context of idiopathic pulmonary fibrosis, IL-33 may also play a role in its pathogenesis." (PMID 39301028, 2024). "Additionally, IL-33 has been implicated in the bleomycin (BLM) mouse model of pulmonary fibrosis with germline ST2 deletion, IL-33 neutralising antibodies and sST2 all leading to reduced lung fibrosis in vivo." (PMID 36949463, 2023). "Therefore, the timing and context of IL-33 blockade are critical in pulmonary fibrosis, and in the early inflammatory phase, IL-33 may be tissue protective." (PMID 38566909, 2022). "Therefore, IL-33 is a potential target for treatment against pulmonary fibrosis." (PMID 38566909, 2022). "Interestingly, peripheral recruitment of ST2 positive cells by IL-33 seems to be one of the prevalent factors driving this observation, as selective bone-marrow ST2 deficiency was sufficient to protect mice from bleomycin lung fibrosis." (PMID 34093523, 2021). "IL-33 has been proposed to participate in the development of lung fibrosis in bleomycin-induced mouse models, and it will be of interest to further explore whether IL-33 is involved in other models of extracellular matrix deposition in the lung or different tissues." (PMID 33376451, 2020). "However, the detailed molecular mechanism of IL-33 mediating weight loss and skeletal muscle atrophy through regulating whole-body metabolism during lung injury, including VILI, chronic COPD, and lung fibrosis, remains unknown." (PMID 31049028, 2019). "Regulation of this IL-33/ST2 axis may attenuate pulmonary fibrosis and enhance recovery." (PMID 29988569, 2018). "Hence, IL-33 is thought to be a novel cytokine that promotes the initiation and progression of pulmonary fibrosis by recruiting and directing inflammatory cell function and enhancing pro-fibrogenic cytokine production in an ST2- and macrophage-dependent manner." (PMID 30405626, 2018). "Furthermore, gene-delivery of Il33 exacerbates bleomycin-induced pulmonary fibrosis." (PMID 26549942, 2015). "Homozygous genetic deletion, or knockout (KO), of either IL-33 (IL33KO), ST2 (ST2KO), or both (IL33KOST2KO, or double-knockout [DKO]) attenuates the magnitude of bleomycin-induced pulmonary fibrosis." (PMID 41465219, 2025). "Exploration of IL-33 in Other Diseases: Expand research on IL-33 involvement in type 2-related respiratory diseases like ARDS and pulmonary fibrosis." (PMID 39301028, 2024). "ILC2s are recruited through the IL-33/ST2 pathway and contributed to fibroblast activation to promote lung fibrosis." (PMID 39405112, 2024). "Mechanistic studies revealed that NFATc3 is involved in the pathogenesis of pulmonary fibrosis by promoting CCL2 and CXCL2 production in response to damaged epithelial cells, IL-33 and Th2 cytokine stimulation." (PMID 37523510, 2023). "IL‐25/IL‐33/TSLP and their corresponding receptors, that is, IL‐17BR/ST2L/TSLPR, are shown to be up‐regulated both in IPF patients and bleomycin (BLM)‐induced lung fibrosis mice model." (PMID 36082495, 2022). "We have done a literature search using the following terms: (“idiopathic pulmonary fibrosis” OR “IPF” OR “lung fibrosis”) and (TSLP or “thymic stromal lymphopoietin” or IL‐25 OR IL‐17E OR IL‐33) from the database of PubMed published in English up to July 2018." (PMID 36082495, 2022). "As an alarmin that forms in response to damage or stress signals, IL-33 is increased in several inflammatory and fibrotic lung diseases that include COPD, idiopathic pulmonary fibrosis (IPF), post-COVID lung fibrosis, and RA-ILD." (PMID 35717175, 2022).
pulmonary fibrosis (continued). "It has been well elucidated that IL‐25/IL‐33/TSLP plays an important role in allergic airway inflammation and remodeling, whereas their roles in idiopathic pulmonary fibrosis (IPF) still remained largely unclear." (PMID 36082495, 2022). "For example, the favorable group for pulmonary fibrosis includes IL-1β, IL-4, IL-6, IL11, IL-13, IL-17A, IL-15, and IL-33; in contrast, the other group with anti-fibrotic function has IL-7, IL-10, IL-12, and IL-27." (PMID 35082682, 2021). "For a more thorough characterization and verification of the 10-4ABFP cells, cytokines elevated during pulmonary fibrosis (TGF-β1, IL-33, IL-4, and TSLP) were screened to establish dose- and time-response curves." (PMID 33162897, 2020). "According to these findings, the expression of IL-33 mRNA is reported to increase in the primary pulmonary fibroblasts from patients with SSc-ILD, as well as in those from patients with idiopathic pulmonary fibrosis (IPF)." (PMID 32679721, 2020). "In addition, both cytokines can also induce the expression of Atrogin-1 and MuRF1, suggesting that BLM-induced lung fibrosis in mice may influence the proteolysis of long-distance muscle tissues through the circulation of both IL-6 and IL-33 secreted from injured lungs during lung fibrosis." (PMID 31049028, 2019). "Recently studies employing animal models proved that IL-25, IL-33, and TSLP have an emergent role in the generation of pulmonary fibrosis." (PMID 31581688, 2019). "The lung fibrosis-related cytokines IL-6 and IL-33 were significantly increased in the blood of mice with BLM-induced lung injury by day 14 compared with the control mice, indicating that IL-6 and IL-33 may associate with lung injury and muscle wasting in BLM-induced lung fibrosis mouse models." (PMID 31049028, 2019). "IL-33 can regulate deposition of extracellular matrix (ECM) and promote the process of pulmonary fibrosis by inducing the imbalance between MMP9 and tissue inhibitor of MMP9 (TIMP-1)." (PMID 30405626, 2018). "Specifically, it has been documented that IL-33 and BLM result in synergistic effects on pulmonary fibrosis in vivo." (PMID 30405626, 2018). "Conceptually, this report supports and expands our long-standing notion that pulmonary fibrosis is not necessarily predominantly driven by the conventional IL-33/ST2 cytokine/receptor axis." (PMID 41465219, 2025). "respiratory disease dataset, we observed significant enrichment of IFNγ signatures in cystic fibrosis and COVID‐19 infection, IL‐33 in COPD and COVID‐19, IL‐4 + IL‐13 in pneumonia, and TGFβ signatures in pulmonary fibrosis (PF) and chronic rhinosinusitis (CRS)." (PMID 40926620, 2025). "In conclusion, IL-33 has no ST2-dependent effects on human lung fibroblasts in vitro nor does it act as a major fibrotic mediator in either the BLM mouse model of pulmonary fibrosis or human PCLS." (PMID 36949463, 2023). "Taken together, these data suggest that the IL-33:ST2 axis does not represent a central pro-fibrotic pathway in the BLM mouse model of pulmonary fibrosis." (PMID 36949463, 2023). "Recent data demonstrated that epithelial cell-derived IL-33 induced production of AREG in Th2 cells leading to enhanced eosinophil activation and expression of osteopontin, which might be involved in lung fibrosis." (PMID 35418991, 2022). "We found that challenge with Poly dA:dT did not induce IL-33 release from PBMCs obtained from either patients without lung fibrosis-like or with lung fibrosis-like changes." (PMID 35844548, 2022). "Genetic ablation of ST2, administration of anti-IL-33, or lentiviral overexpression of the sST2 decoy receptor during the inflammatory phase of the BLM model attenuated IL-13, IL-33, and TGF-β expression while halting pulmonary fibrosis and improving survival rates in BLM-treated mice." (PMID 38566909, 2022). "Similarly to IL-25 or TSLP, IL-33 can be found in increased concentrations in the BAL and lung tissue of IPF patients and is upregulated in experimental lung fibrosis." (PMID 34093523, 2021).
pulmonary fibrosis (continued). "Interestingly, ST2 depletion protects mice from developing bleomycin-induced lung fibrosis, suggesting that recruitment of ST2+ immune cells by IL-33 is an important factor driving fibrogenesis." (PMID 34685744, 2021). "IL-33/ST2 signaling is involved in various types of lung disease, including ventilator-induced lung injury (VILI), chronic obstructive pulmonary disease (COPD), and lung fibrosis." (PMID 31049028, 2019). "The increase in IL-33 responsive ILC2s is not unique to animal models of pulmonary fibrosis since they are also increased in SSc, correlating with the extent of fibrosis." (PMID 30405626, 2018). "In this model IL-33 activates M2 macrophages to produce IL-13 and TGF-β1, and then further induces the expansion of ILC2s to produce IL-13, ultimately resulting in the development of pulmonary fibrosis." (PMID 28271447, 2017). "Innate T helper type 2 (Th2) immune responses mediated by interleukin (IL)-33, thymic stromal lymphopoietin (TSLP), and IL-25 have been shown to play an important role in pulmonary fibrosis of animal models; however, their clinical implications remain poorly understood." (PMID 28202030, 2017). "In addition to IL-33, TSLP has emerged as a candidate cytokine in the pathogenesis of pulmonary fibrosis by the elevated TSLP levels seen in both systemic sclerosis." (PMID 28202030, 2017). "IL-33 and ST2 have been demonstrated to play a role in pulmonary fibrosis in vivo." (PMID 27001429, 2016). "Indeed, not only the proteolytically mature IL-33 (MIL33) cytokine acting through ST2 but also the full-length IL-33 (FLIL33) precursor in the complete absence of ST2 promotes pulmonary fibrosis." (PMID 41465219, 2025). "In the middle and late stages of the disease, IL-33 induces ILC2 hyperactivation, differentiation of alternately activated M2 macrophages, and the secretion of TGF-β and IL-13 from mast cells, resulting in the transformation of epithelial cells to mesenchymal cells and leading to pulmonary fibrosis." (PMID 36362440, 2022). "Although we also found that the increasing activity of AMPK in skeletal muscle may be due to the effect of IL-33 in serum, we could not rule out the activation of AMPK caused by hypoxia because of reduced lung function in lung fibrosis mice." (PMID 31049028, 2019). "It is well established that the pro-fibrogenic activity of IL-33 is mainly attributed to its involvement in M2 macrophage polarization, as macrophages with alternative activation, rather than classical activation, serve to accelerate pulmonary fibrosis." (PMID 30405626, 2018). "The observations on IL-33 activity in the lung with an impact on TH2 responses and tissue repair make it highly likely that IL-33/ST2 signaling may also impact on radiation-induced lung fibrosis." (PMID 28018357, 2016).
melanoma (72 papers, 2018 to 2025). A malignant, usually aggressive tumor composed of atypical, neoplastic melanocytes. "The transcription factor SOX10 and the cytokine IL-33, both previously implicated in melanoma progression, were consistently overexpressed." (PMID 40647405, 2025). "-Influences IL-1β, IL-6, and IL-33 plasma levels.-Protective against sporadic malignant melanoma.-Increased susceptibility to Mycobacterium tuberculosis infection in HIV-positive patients." (PMID 38920661, 2024). "The IL-33/ILC2/eosinophil axis-mediated antitumor effect was also reported in association with levels of lactate produced by melanoma cells." (PMID 34209038, 2021). "Moreover, IL‐33 has been implicated in the pathogenesis of melanoma by promoting vascular mimicry (VM)." (PMID 38775220, 2024). "However, data from patients with melanoma show some contradictory results: higher IL-33 levels are associated with better survival rates within 80 months." (PMID 33628592, 2021). "However, pathways enriched in the high IL-33 group of the primary melanoma sub-cohort are less associated with the immune response." (PMID 33621202, 2021). "We first evaluated the direct anti-tumor effects of the combination of DAC with IL-33 on mouse and human melanoma 3D cultures." (PMID 40317004, 2025). "Given its DNA methylation inhibition activity, we conducted methylation-specific quantitative PCR (MSP-qPCR) analysis of il33 gene promoter P1 in B16.F10 and IL33 gene promoter P in A375M melanoma cells treated with DAC." (PMID 40317004, 2025). "In this setting, human A375M melanoma cells treated with DAC/IL-33 attracted more PBMCs, including many CD8 T cells, with respect to A375M cells exposed to single treatments or left untreated." (PMID 40317004, 2025). "Here, we show that DAC induces IL33 promoter specific demethylation in both mouse and human melanoma cells." (PMID 40317004, 2025). "Methylation studies indicated that DAC increased the expression of IL-33 in mouse and human melanoma cells through demethylation of a transcription factor binding site located inside the IL33 gene." (PMID 40317004, 2025). "MTS assays on 2D cultures confirmed that DAC exhibited dose-dependent anti-proliferative effects on both mouse B16.F10 and human A375M melanoma cells independently of IL-33." (PMID 40317004, 2025). "In melanoma, a number of reports indicates that IL-33 promotes anti-tumor immune responses by recruiting and/or activating eosinophils, dendritic cells (DC), type- 2 innate lymphoid cells (ILC2), NK and CD8 T cells in vivo." (PMID 40317004, 2025). "In the present study, we demonstrate a co-operative action of DAC with exogenous and endogenous IL-33 signaling to promote tumor-immune crosstalk in melanoma." (PMID 40317004, 2025). "Exposure to DAC dose-dependently increased the expression of IL33 gene in mouse B16.F10 and human A375M melanoma cells with respect to controls." (PMID 40317004, 2025). "After 24 h exposure to 0.1 μM DAC, B16.F10 melanoma cells exhibited significant demethylation (7-fold increase with respect to untreated cells) of il33 gene promoter P1." (PMID 40317004, 2025). "The overexpression of the IL33 gene in both methods further supports its potential role in melanoma progression." (PMID 40647405, 2025). "In melanoma, endogenous and exogenous IL-33 exert anti-tumor effects through the stimulation of several immune effector cells." (PMID 40317004, 2025). "In this study, we explored the potential synergistic role of DAC with IL-33/ST2 axis against melanoma." (PMID 40317004, 2025). "In vivo, DAC combined with IL-33 reduced tumor growth and prolonged the survival of mice transplanted with melanoma cells, outperforming single treatments." (PMID 40317004, 2025). "Following incorporation of EV from IL-33 activated eosinophils, melanoma cells underwent transcriptional reprogramming by increased expression of cyclin-dependent kinase genes and up-regulation of E-Cadherin, while down-modulating N-Cadherin." (PMID 40050933, 2025).